KRT14 (keratin 14)
Diseases named in the same sentence as KRT14 in open-access papers (continued):
Sharing a sentence is not in itself a finding about the gene and the disease.
tumor (continued). "For A1708E, previously shown to be functionally compromised, analysis of oestrogen receptor, cytokeratin 5/6, and cytokeratin 14 tumour expression data significantly strengthened the prediction of pathogenicity, giving a posterior probability of pathogenicity of 99%." (PMID 18036263, 2007). "We used a combination of keratin 14 staining, which is commonly expressed in keratinocyte-derived neoplasias, and phalloidin, which strongly stains cortical F-actin in tumour cells, to delineate the tumour boundary." (PMID 15597106, 2005). "Furthermore, si-m/hVDAC1-B reduced the expression levels of cancer-stem-cell-related proteins (cytokeratin-14, ALDH1a), modifying the tumor microenvironment, including decreased angiogenesis, extracellular matrix, tumor-associated macrophages, and inhibited epithelial–mesenchymal transition." (PMID 38607066, 2024). "Notably, treatment with ADV-ApoA1 markedly diminished the transcription of KRT14 in tumor tissues." (PMID 38566092, 2024). "Moreover, the presence of “anti-cancer” next to “pro-tumorigenic” within a single tumor only complicates the final conclusion regarding AP-2 role in that cancer (e.g. KRT14 vs GRIA1, SEZ6L, SLC12A5 for AP-2α within PAAD or NTSR1 vs PPEF1 for AP-2γ within LUAD)." (PMID 35361846, 2022). "Therefore, we used a stemness gene associated with tumor cell heterogeneity and SOX2, SOX4, SOX9, basal cell markers KRT5, KRT14, immune genes PD-Ll and epithelial-mesenchymal transition E-cadherin to study heterogeneous cell and malignant transformation mechanisms." (PMID 36056339, 2022). "Compared to either untreated or non-targeting controls, cells lacking HRNR or CDCA8 showed significantly reduced proliferation; by contrast, the loss of KRT14 did not affect proliferation, suggesting that it was not required for tumour cell viability or growth." (PMID 31443478, 2019). "Note that these tumours arose from the same cell populations simultaneously expressing KRT5 and KRT14." (PMID 41507151, 2026). "We established the cell cluster identity using the SingleR tool and confirmed the identified tumor clusters based on the expression of CDKN2A and KRT14 for SCC." (PMID 40597205, 2025). "Consistant with the orthotopic tumor, ADV-ApoA1 treatment of mice resulted in a decrease in p-IκB, p65, and KRT14 in the metastasis c tumors." (PMID 38566092, 2024). "Pairwise analysis revealed that tumor tissues exhibited significantly elevated expression of KRT81, KRT6A, KRT17, and KRT14, which were positively correlated with FSTL3 expression, compared to that in normal tissues." (PMID 38240936, 2024). "In the case of other types of KRT (KRT13, KRT14, KRT24) in HNSCC, OSCC, and neoplastic oral mucosa, decreased protein levels were observed in the tumor sample compared to the margin/healthy tissue, which is consistent with our results." (PMID 39000463, 2024). "Luminal tumours were identified as KRT20+/GATA3+/FOXA1+ and basal tumours as KRT5/6+/KRT14+/GATA3−/FOXA1−." (PMID 39594166, 2024). "This study concluded that basal tumours with KRT5/6, p63, and KRT14 expression had a better response to chemotherapy, while luminal tumours with active PPAR expression and activating mutations in FGFR3 showed expression of KRT20, FOXA1, and GATA3." (PMID 39594166, 2024). "Quantification of GPx2 KD tumours and paired lung mets confirmed a higher percentage of carcinoma cells co-expressing p63 with KRT8/KRT14 than with KRT8 or KRT4 at both sites." (PMID 38238426, 2024). "Several well-known tumor markers for HNSCC were highly expressed in almost every cell cluster, including Keratin 6A (KRT6A), Keratin 14 (KRT14), and Cadherin-1 (CDH1)." (PMID 36982384, 2023). "PADI4 upregulates the expression levels of KRT14, CXCR2 and TNF-α, which are related to cell proliferation, cell migration, tumour angiogenesis, and tumour immune microenvironment." (PMID 35045833, 2022).
tumor (continued). "The differential gene expression levels between tumor and adjacent tissue displayed in the box plot showed that LAMB3, KRT14, KRT16, KRT17, and KRT6B expression levels were significantly (p < 0.001) higher in normal tissues than in tumors." (PMID 36293530, 2022). "Tumor cells can be divided into 4 different subtypes, including basaloid cells (KRT5, KRT14), myoepithelial cells (ACTA2, MYL), cycling cells (MKI67, TOP2A) and duct-like cells (KRT7, KRT19)." (PMID 35860547, 2022). "We demonstrate that a subset of tumor cells, featuring medullary thymic epithelial cell (TEC) phenotype and marked by KRT14/GNB3 expression, accumulate in type 1 TETs, while T-cell positive selection is inhibited." (PMID 36115836, 2022). "This revealed that GPx2 KD further enriched cluster 5 in basal/mesenchymal-like genes (KRT14, ITGA6, FGFR1, COLA9A3, S100s) relative to cluster 5 in control tumor." (PMID 35193955, 2022). "A reduced number of tumour cells that express Keratin 14 and SMA were detected in tumours with reduced Sox11 levels compared to controls." (PMID 33969421, 2021). "Compared to controls, tumor displaying lower SNAI1, PECAM1 and VIM and higher TP63, KRT14, KRT5 and PTPRC (CD45) RNAs (PyMT-VE-CadhSnail1KO tumor signature) presented a longer overall survival, strengthen our mice results." (PMID 34335957, 2021). "LAMC2, an isoform of the laminin family, and the KRT14, KRT16, and KRT17 hemi-desmosomal proteins play crucial roles in tumor cell stability and filament formation anchorage, migration, and proliferation." (PMID 32922662, 2020). "Consistently, GATA6 was significantly lower in BAS-L tumours (p<0.001), and GATA6-silenced PaTu8988S cells ectopically expressed the basal keratins KRT5 and KRT14." (PMID 27325420, 2017). "The greater the expression level of the KRT14 and ETS2 genes in the tumor tissues relative to the normal tissues, the greater would be the chance of recurrence." (PMID 25575813, 2015). "Cytokeratin 14 (KRT14), a basal cell marker, was seen at high levels in HBE, in the ASC CSLC, and at much lower levels in the AC CSLC and tumor stroma." (PMID 24324581, 2013). "Regarding the expression of luminal and basal biomarkers, Layer3.1 tumor presented higher expression of KRT20, a luminal-papillary biomarker, whereas Layer3.2 had higher expression of KRT5, KRT6a, KRT14, and CD44 basal biomarkers, but also PGM5, DES, and SGCD luminal-infiltrated biomarkers." (PMID 41516353, 2026). "In SOX2-expressing tissues such as the oral mucosa and salivary glands, deletion of Sox2 in KRT14-Cre–driven models did not impair tumor formation, growth kinetics, or histological identity." (PMID 41266112, 2026). "SPRR1B is co-expressed with keratin genes (KRT14, KRT6B), which may promote tumor invasion by regulating EMT." (PMID 40568599, 2025). "CRABP2, KRT14, and CEBPA expressions were significantly increased in STAS tumor cells." (PMID 40786043, 2025). "We triple co-immunostained tumours for p63, KRT8 (luminal) and KRT14 (basal) markers." (PMID 38238426, 2024). "Namely, PyMT2/GPx2OE tumours were negative for KRT8/KRT14/pAMPK/GLUT1 as compared to control tumours which were KRT8/pAMPK positive." (PMID 38238426, 2024). "Luminal tumours were (GATA3, FOXA1+), and basal/squamous tumours were (KRT5/6, KRT14+)." (PMID 39594166, 2024). "In addition to the cell-intrinsic effects mediated by KRT14, it has been discovered that cholesterol induces CD8+ T cell exhaustion in the tumor microenvironment (TME)." (PMID 38566092, 2024). "To examine whether phenotypic and metabolic plasticity were interrelated, we co-stained tumours for luminal (KRT8; yellow) and basal (KRT14; red) markers, along with OXPHOS (pAMPK; green) and glycolysis (GLUT1; blue) markers." (PMID 38238426, 2024).
tumor (continued). "Of note, GATA3 and KRT14 were not considered in this study, as they were present in either most or almost no tumor samples, respectively." (PMID 39337385, 2024). "Through assay for transposase-accessible chromatin using sequencing (ATAC-seq), we detected increased chromatin openness of squamous markers (TP63, KRT5, KRT6A and KRT14) and reduced chromatin accessibility of adenomatous markers (KRT7 and MLPH) in the DR tumor cells." (PMID 39687207, 2024). "We confirmed the upregulation of PD-L1 in tumor cells (cytokeratin-14 positive) and non-tumor cells (cytokeratin-14 negative) by using immunofluorescence staining." (PMID 39567998, 2024). "Co-expression of GFP and Krt14 was also observed, with about 50% of basal marker-expressing cells co-expressing GFP (mean = 47.79%), confirming the luminal lineage of these basal-like tumor cells." (PMID 36859337, 2023). "Additionally, when tumor cells undergo EMT, the expression of differentiation-specific keratins, such as Krt14, is downregulated, as found in models of cervical melanoma." (PMID 36647127, 2023). "However, tumor cells in tumor 3 expressed S100A7, FABP4, and KRT14, and GO analysis showed that complement activation, epithelial cell differentiation, and negative regulation of growth were highly enriched." (PMID 36569924, 2022). "In addition, the highly phosphorylation (e.g., HSPB1 S82, KRT14, KRT13 S427, etc.)were both detected in tumor tissues and their paired normal tissues in EESCC." (PMID 35397555, 2022). "Using unsupervised hierarchical clustering of six subtyping genes assessed by multiplex RNA hybridization (basal differentiation: KRT5, KRT14, CD44; luminal differentiation: KRT20, GATA3, and FOXA1), 28 tumor samples were each classified as either basal or luminal subtypes." (PMID 36142180, 2022). "Unlike KRT14+ epithelial/tumor cells, all other nonepithelial cell types did not drift or cluster independently from each other regardless of donor." (PMID 35687691, 2022). "To define the epithelial/tumor cellular landscape of human BCC and PTS samples, we subclustered 30,058 KRT14+ epithelial-derived cells (kPTS = 5146 versus kBCC = 24,872) and identified 15 coarse-grained epithelial cell clusters, all defined by expression of unique gene biomarkers." (PMID 35687691, 2022). "Notably, we found p-EMT tumor cells (p-EMT sub-cluster) that highly expressed CDH1 (E-cadherin), keratin KRT14/16/17, TP63 (Tumor protein p63), and basement membrane ECM glycoprotein- Laminin family (LAMC2, LAMB3, LAMA3...)." (PMID 35742914, 2022). "In agreement with our previous findings, KRT14 staining was localized to tumor epithelium, with little evidence of KRT14 in stromal tissue." (PMID 34470672, 2021). "The majority of pure pTa HG/papillary pT1(a) HG samples exhibited a luminal-like phenotype, i.e., positivity for KRT20 and a lack of basal cytokeratin (KRT5/6 and KRT14) expression in tumor cells." (PMID 32445084, 2020). "The 2 exceptions to this are KRT14 and KRT17, both of which are heavily up-regulated in the tumor." (PMID 33142242, 2020). "Cell types within these invasive structures are distinguished by Keratin 14 expression: Keratin 14 positive (K14+) cells lead collective invasion strands, while Keratin 14 negative (K14−) cells form the bulk of the organoid or primary tumor." (PMID 31961880, 2020). "Similar to the immunostaining results of tumor tissues from BC patients, TFCP2L1‐expressing cells in xenograft samples showed a high concurrence with cells stained with the bladder CSC markers including CD44, KRT14, and SALL4." (PMID 31709755, 2020). "Notably, though, all overexpressed keratins, i.e. KRT5A, KRT6A, KRT7, KRT14, KRT17, were found to play a role as LUAD tumor progression determinants." (PMID 30473748, 2018). "Notably, all overexpressed keratins, i.e. KRT5A, KRT6A, KRT7, KRT14, KRT17, were found to play a role as LUAD tumor progression determinants." (PMID 30473748, 2018).
tumor (continued). "In agreement with the columnar differentiation displayed by all these tumours, the expression of Krt16 and other squamous markers such as p63 and Krt14 (data not shown) was never detected." (PMID 29700411, 2018). "Furthermore, we analyzed the expression levels of these markers in the tumor samples retrieved from MBZ or DMSO-treated animals, and found that except keratin 14 all of the other markers expressed significantly higher in MBZ-treated samples." (PMID 28099902, 2017). "A transactivation mutant of c-Jun (TAM67) expressed under the Keratin 14 promoter or an inducible system produces a thickened, hyperproliferative, parakeratotic epidermis, but the epidermis is resistant to DMBA/TPA-dependent tumor formation." (PMID 24796531, 2014). "Cytokeratin-14, studied in breast samples, was expressed neither in the tumor of origin nor in the related cell cultures." (PMID 24098684, 2013). "Notably, tumor characterization in these models revealed three distinct tumor types in Ad-K8-Cre-injected mice (i.e., Type 1: KRT8+KRT14− luminal tumor cells surrounded by KRT14+KRT8− basal tumor cells; Type 2: KRT8/KRT14 double-positive; Type 3: KRT8+KRT14− luminal only)." (PMID 40622584, 2025). "Indeed, echinomycin-treated GPx2 KD tumours were negative for GLUT1, pAMPK and KRT14 but retained KRT8 expression relative to vehicle-treated GPx2 KD tumours which were positive for all four markers." (PMID 38238426, 2024). "Interestingly, most of the cells co-expressing GFP and Krt14 also co-expressed Krt8, suggesting that these tumor cells do not completely lose their luminal identity, but instead gain a lumino-basal phenotype." (PMID 36859337, 2023). "Notably, a compelling correlation is observed between TNBC tumor cells and the basal-like subtype, as evidenced by their shared high expression of the epidermal growth factor receptor (EGFR) and the keratin family members KRT5, KRT17, and KRT14." (PMID 37627192, 2023). "Hence, our results suggest a potential functional signaling network of TMEM119+ FIBs with KRT14+ tumor cells driven through paracrine noncanonical WNT signaling." (PMID 35687691, 2022). "In contrast, residual tumor cells in the Wnt1 model did not exhibit increased expression of mesenchymal markers and instead displayed increased expression of the basal epithelial marker Krt14 (CK14) along with luminal epithelial markers Epcam and Cdh1." (PMID 34088357, 2021). "Staining was localised to the tumour epithelium, with little evidence of KRT14 in stromal tissue." (PMID 31443478, 2019). "The expression of KRT5 / KRT14 pairs is closely related to the intermediate phenotype of cells that undergo the epithelial-mesenchymal transition (EMT), which has a significant effect on tumor progression and metastasis because it helps to spread tumor cells throughout the body." (PMID 29377892, 2018). "However, transgenic overexpression of mutant Ras by the Keratin-14 or -5 promoter, which are expressed in all epithelial cells, leads to broad hyperproliferation and early death rather than physiologically relevant tumor formation." (PMID 26573149, 2015). "In addition, levels of the differentiation markers KRT10 and KRT14 and senescence marker SA‐β‐gal were upregulated at the boundary of the tumor in UVB‐exposed wild‐type mice, suggesting that SASP activation and carcinogen‐stimulated tumor formation resulted from cell senescence." (PMID 31755176, 2020). "Moreover, this study found that PADI4 may contribute to cancer development and progression by increasing the expression of CXCR2, KRT14 and TNF-α, which activate pro-inflammatory processes, angiogenesis, cell migration, cell proliferation and cell differentiation in tumor tissues." (PMID 27556695, 2016). "Carcinomatous differentiation was characterized by islands and trabecules of polygonal cytokeratin AE1/AE3-positive and p63-, cytokeratin 14-negative, SMA-negative, and vimentin-negative tumor cells with moderate anisocytosis and anisokaryosis." (PMID 40509039, 2025).
tumor (continued). "In contrast, genes with higher expression in HET/no pCR samples included basal cytokeratins (KRT5, KRT14, and KRT17), suggesting possible tumor subtype–related differences." (PMID 38300710, 2024). "Immunostaining revealed that GPx2 KD tumours contained carcinoma areas that were KRT14, N-CAD, VIM positive and E-CAD negative as compared to control tumours, indicative of binary EMT." (PMID 38238426, 2024). "These tumours also on the protein level typically showed no or low expression of KRT5 and KRT14, aberrant expression of KRT20 and a low expression of EGFR, but a high expression of ERBB2." (PMID 30258198, 2018). "One portion of the SCCL/Mes‐Inf cluster was negative for KRT5/KRT14 and FOXA1/GATA3, as well as for CDH3 expression, making it distinct from basal/SCC‐like tumours." (PMID 28195647, 2017). "We investigated the idea that the barrier is formed by normal myoepithelial cells (as opposed to transdifferentiated tumor cells) by staining for HER2 protein, HER2 mRNA and the myoepithelial protein, KRT14." (PMID 29184166, 2017). "An analysis of the immunohistochemical profile of the tumor cells showed positivity for vimentin, S-100 protein, and glial fibrillary acidic protein (GFAP), but not for smooth muscle actin (α-SMA) and cytokeratin 14 (CK14)." (PMID 22152025, 2011). "Notably, most mice reached humane endpoints within 3 wk of tumor detection by BLI, mirroring the rapid progression observed in the KRT14-Cre; NCT models, regardless of the Sox2 status." (PMID 41266112, 2026). "Malignant tumor cells were identified as mesenchymal cells based on their negative immunolabeling for cytokeratin A1/AE3 and their positive vimentin immunoreaction, together with the lack of expression of the MEC markers cytokeratin 14 and p63." (PMID 40509039, 2025). "Notably, canonical breast cell differentiation genes and molecular markers (KRT8, KRT18, KRT14, TP63, ERBB2, ESR1, PGR) were not differentially expressed, suggesting the cells maintain their differentiation state and tumor subtype." (PMID 34741115, 2021). "Interestingly, the trend of the changes in KRT14 levels was different in the samples that had been exposed, or not, to NAC suggesting an impact of the latter on tumor cell phenotype." (PMID 32635360, 2020). "However, these two basal/SCC‐like tumour categories do not differ in their KRT5, KRT14/FOXA1, GATA3 ratios, their defining characteristics, or their shifts to high CDH3 and lower CDH1 expression." (PMID 28195647, 2017).